RN7SKP34 (RN7SK pseudogene 34)
Gene: Miscellaneous RNA gene on chromosome 5 (87,102,603 to 87,102,846, reverse strand). Ensembl gene ENSG00000251951.
Homologues: Orthologues: chimpanzee 7SK (99% identical). Paralogues in human: RN7SKP69 (56% identical), RN7SKP127 (54% identical), RN7SKP137 (53% identical), RN7SKP139 (53% identical), RN7SKP146 (53% identical), RN7SKP163 (53% identical), RN7SKP95 (53% identical), RN7SKP211 (53% identical), RN7SKP230 (53% identical), RN7SKP236 (53% identical), RN7SKP28 (53% identical), RN7SKP85 (53% identical), and 284 more.